BDNF (brain derived neurotrophic factor)
Diseases named in the same sentence as BDNF in open-access papers (continued):
Sharing a sentence is not in itself a finding about the gene and the disease.
depression (continued). "We found a significant negative correlation between the serum BDNF levels with the severity of depression in both drug-treated and non-treated MDD patients." (PMID 32085720, 2020). "Interestingly, based on previous studies, miR-16 is closely related to depression, and the 3′-UTR of BDNF was found to be targeted by miR-16." (PMID 33029119, 2020). "BDNF levelduring acute stroke was negatively correlated with post-stroke depression,while, conversely, acute stroke MDA and 8-OhdG levels were positivelycorrelated with depression." (PMID 32206197, 2020). "Mean serum BDNF level in depressed patients was significantly lower (p < 0.05)than in patients without symptoms of depression." (PMID 32206197, 2020). "Theserum BDNF level of the depressed post-stroke patients was significantly lower thanthe post-stroke patients without depression." (PMID 32206197, 2020). "For example, it has been shown that fluoxetine-induced upregulation of the Brain-Derived Neurotrophic Factor (BDNF), involved in depression pathophysiology, may be mediated by both P1 and P2 receptor signaling." (PMID 32178222, 2020). "Together with BDNF, FGF-2 is a second important growth factor marker in depression." (PMID 33255237, 2020). "In addition, in maternally separated depression rat pups, acupuncture stimulation at HT7 significantly increased the BDNF level of the prefrontal cortex." (PMID 33029119, 2020). "For the time being, there is not enough evidence of a definitive link between BDNF and depression, disability and mortality, and their potential interrelationships need to be confirmed in future studies." (PMID 33213019, 2020). "The negative correlation between Ham-D scores and serum BDNF levels in MDD patients can be used as a predictor for the severity of depression." (PMID 32085720, 2020). "Two meta-analyses reported significantly lower-than-normal-range serum BDNF levels in patients with BD during episodes of mania and depression, but not different from controls during euthymic state." (PMID 32115672, 2020). "Thus, this study investigated the impact of regular leisure-time physical activity on cognitive function (plasma BDNF, NGF, and cathepsin B) and menopausal parameters (the climacterium, depression, and cognitive tests) in obese, middle-aged women." (PMID 33233633, 2020). "BDNF levels in acute stroke were significantly lower in the depression groupthan in the non-depression group (p < 0.05)." (PMID 32206197, 2020). "There is evidence indicating that patients suffering from post-stroke depression reveal significantly lower BDNF level than patients not suffering from this complication." (PMID 31701356, 2020). "The correlation between BDNF level and post-stroke depression was negative andstatistically significant (p < 0.05)." (PMID 32206197, 2020). "In addition, ELS can induce anxiety- and depression-like behaviors via dysregulation of the neuroendocrine system which includes the HPA axis and the serotonergic system, along with changes of brain-derived neurotrophic factor expression." (PMID 33029124, 2020). "On the other hand, a dietary quality assessed with the use of the Australian Dietary Quality Score did not affect the level of BDNF in depression sufferers." (PMID 33343231, 2020). "In addition, PI3k-Akt pathway controlled BDNF (such as IL-6, TNF-α) to reverse depression-like behavior in a neurotrophic and neuroprotective way." (PMID 32997725, 2020). "In addition, BCP improved depression and memory deficit by modulating PGC-1α/BDNF pathway in a CB2R-dependent manner." (PMID 32998300, 2020). "Significant negative correlations between serum BDNF levels and Hamilton depression rating (Ham-D) scores were observed in both drug-naïve and drug-treated MDD patients." (PMID 32085720, 2020). "Treatment with fluoxetine (SSRI) was found to alter BDNF levels in patients with depression, whereas venlafaxine did not." (PMID 31231295, 2019).
depression (continued). "We evaluated the serum BDNF levels in acne vulgaris patients with and without depression and compared with age-matched healthy control subjects." (PMID 31234814, 2019). "It was found that SNS may up-regulate CYP1A2, CYP2D1, CYP2E1, and CYP3A2 activity to reduce IL-6 and TNF-α expression, as well as up-regulation of BDNF and its receptor TrkB, reduce IL-1β, IL-6, and TNF-α expression to treat depression." (PMID 32009949, 2019). "Regarding BDNF, the difference was not significant between groups A and C. Nonetheless, there was a significant difference in depression, anxiety, stress, and craving between two groups." (PMID 32477481, 2019). "In previous studies, Sun et al98 found that SYG administration could alleviate depression in TST and FST, as well as regulate CORT levels of learned helplessness rats and BDNF levels in the hippocampus of CMS rats." (PMID 31599060, 2019). "A10-day-AAV treatment could alleviate depression-like behaviors in mice, and AAV delivery of BDNF striatal neurons induced neurogenesis and increased the lifespan of an animal model of HD." (PMID 31440144, 2019). "In our sample, baseline serum BDNF levels did not predict major depression and the clinical characteristics of the patients did not predict their BDNF levels." (PMID 31231276, 2019). "Decreased levels of BDNF-TrkB signaling pathway were often reported in depressed subjects, and up-regulation of BDNF-TrkB via pharmacological agents in the prefrontal cortex (PFC) and hippocampus can confer resilience to inescapable stress and alleviate depression symptom." (PMID 32116688, 2019). "Accumulating evidence has verified that CUMS participated in the development of depression following various molecular and cellular mechanisms, and regulated the neurotransmitter content and the cAMP-CREB-BDNF (brain-derived neurotrophic factor) signaling pathway." (PMID 30625977, 2019). "The serum BDNF levels were markedly decreased in patients with depression compared with patients without depression and healthy cases (10.96 ± 2.12 vs. 13.85 ± 2.47, 10.96 ± 2.12 vs. 14.35 ± 2.70, respectively; P ≤ 0.05)." (PMID 31234814, 2019). "The BDNF and phosphatidylinositol 3 kinase (PI3K)/protein kinase B (AKT) pathways not only regulate the growth and survival of neurons in the hippocampus, but also regulate stress-induced depression and antidepressant response." (PMID 31130833, 2019). "Although BDNF was initially proposed as a therapeutic alternative for depression, clinical trials with recombinant BDNF have failed to achieve significant antidepressant efficacy." (PMID 30719038, 2019). "Hence, low BDNF may be associated with higher cardiac risk independent of depression." (PMID 31659205, 2019). "One of the most robust and sustained mechanisms involved in the exercise-induced antidepressant effect is the elevation of hippocampal brain-derived neurotrophic factor (BDNF) mRNA levels during voluntary exercise in normal rats and also in an animal model of depression." (PMID 30792631, 2019). "In univariate analysis, acne vulgaris patients with depression had lower family annual income, higher probability of family history of acne vulgaris, dropping out from school and currently unemployed, higher AIS score, higher DLQI score, and lower BDNF levels." (PMID 31234814, 2019). "Synaptic regulators, such as BDNF/tropomyosin receptor kinase B (TrkB), N-methyl-d-aspartate (NMDA), glutamate, estrogen, insulin, or their downstream signaling pathways, like PI3K/AKT/mTor are crucial therapeutic targets for depression." (PMID 31338119, 2019). "The stimulation of the left DLPFC (group A) significantly reduced depression, anxiety, stress, and craving compared with the sham group, while there was no change in BDNF." (PMID 32477481, 2019). "The vast majority of studies have found abnormally lower serum BDNF levels in patients with depression than that of people without depression." (PMID 31231295, 2019).
depression (continued). "The authors observed that the increase in serum levels of mature BDNF and precursor pro-BDNF correlated negatively with the severity of depression, but not PTSD symptoms." (PMID 31098654, 2019). "BDNF and NGF are among the best characterized neurotrophins in terms of its role in synaptic plasticity, as well as its potential role in the pathology and treatment of a variety of psychiatric disorders including depression." (PMID 30155683, 2019). "Furthermore, σ1R upregulates neurotrophic factors such as brain-derived neurotrophic factor (BDNF) and nerve growth factor (NGF), proteins whose regulation and expression seem to be involved in the pathophysiology of depression." (PMID 29903051, 2019). "Although many studies have shown that depression roles in acne vulgaris, there is no comprehensive study on BDNF levels in acne vulgaris patients with depression." (PMID 31234814, 2019). "The effect of some antidepressant in the increased serum level of BDNF does not parallel clinical improvements such as the severity of depression symptoms." (PMID 31118969, 2019). "Although we did not observe any significant associations in this study, other genetic association studies have also shown that unlike subjective CRCI, anxiety, fatigue, and depression are not ameliorated but worsened among BDNF Met carriers." (PMID 30382534, 2019). "This seems to support the concept that the main determinant related to lower BDNF levels in depression and mania is the presence of symptoms, not medication status." (PMID 31379619, 2019). "Further investigation on the interaction between BDNF/NTRK2 and dopamine signaling in the brain is crucial for understanding not only the effect of stress on depression, but also for addictive behavior in the functional reorganization of neuronal networks in addiction and psychiatric disorders." (PMID 30765816, 2019). "So far, differential BDNF methylation initially found in blood, was confirmed to be also present in saliva for bipolar disorder, anxiety and depression, but has not been investigated for BPD yet." (PMID 30134995, 2018). "The higher level of soluble sortilin in depressive patients is correlated with an increase of BDNF and VEGF levels, indicating that the circulating soluble sortilin could be a new candidate as a biomarker of depression state." (PMID 30127743, 2018). "Depressed patients have lower BDNF levels compared with non-depressed subjects; therefore, one of therapeutic strategy for treating depression is to upregulate the BDNF expression." (PMID 30364169, 2018). "The positive link between BDNF and locomotor activity has been examined largely in the context of animal models of depression, but not explicitly for the motivated behavior of voluntary wheel-running." (PMID 29370799, 2018). "Results of negative mood (anxiety and depression) and negative cognitive style to pain (pain catastrophizing) stratified by group and BDNF Val66Met genotype." (PMID 30524221, 2018). "The relationship of BDNF to pathophysiology of depression or anxiety disorders and the mechanism of drug action remains to be determined, although, it seems that escitalopram do not change serum BDNF levels." (PMID 29799860, 2018). "FLX makes no exception in this regard, and upon BDNF haploinsufficiency its action on behavioural model of anxiety and depression is lost." (PMID 29379096, 2018). "This led us to conclude that the 5-TH1A/CREB/BDNF pathway is not strongly involved in the mechanism by which estrogen improves anxiety and depression in this mouse model." (PMID 30589890, 2018). "BDNF+/- mice offer a good model to study non-conventional therapeutic strategies for anxiety and depression since these mice are less prone to respond to currently available antidepressant drugs including SSRIs." (PMID 30622454, 2018). "Thus, the local infusion of BDNF in the hippocampus mimics the behavioral effects of antidepressants, whereas the intra-VTA infusions of BDNF produce a depression-like effect." (PMID 30477252, 2018).
depression (continued). "It is noteworthy, however, that the way in which BDNF is involved in the pathogenesis of depression has not yet been precisely established." (PMID 30477252, 2018). "Therefore, it is likely that the A. philoxeroides extract ameliorated depression-like behaviors in OVX mice via stimulation of CREB- and BDNF-mediated neuroplasticity and neurogenesis in the hippocampus and frontal cortex." (PMID 30200295, 2018). "Furthermore, Pearson’s test revealed a potential relationship between the depression-like behavior, the plasma CRP concentration, and the protein expressions of BDNF, Copine 6, synapsin I, or synaptotagmin I in the hippocampus or the PFC." (PMID 30429764, 2018). "Our previous researches revealed that total glycoside fraction of peony could clearly increase BDNF protein and gene expression levels in the hippocampus of the CUMS rats and the cortisone-induced depression model rats." (PMID 30692946, 2018). "Previous literature has shown a correlation between depression and CREB/BDNF signaling; therefore, we examined whether FX extract affects the activity of CREB and BDNF in this animal model." (PMID 30065945, 2018). "Serum PE concentration may be used as a specific biomarker in addition to sortilin, BDNF, and VEGF to validate the remission of depression after ECT in TRD patients." (PMID 30233189, 2018). "Given the central role of p38 and JNK signaling pathways in the regulation of neuroinflammation and depression, further studies are required to determine the relationship between the cAMP/PKA/CREB/BDNF and p38/JNK signaling pathways and their relative roles in LPS-induced depressive-like behaviors." (PMID 29419799, 2018). "Depressive disorders are a common comorbidity of CFS, suggesting the intriguing possibility that BDNF may play a role in the pathogenesis of CFS." (PMID 29643935, 2018). "Upregulation of the expression of BDNF-TrkB-CREB and the pCREB DNA activity in the hippocampus could contribute to the antidepressant effects of HJDT, manifested as improvement of depression-like behaviors." (PMID 28694833, 2017). "Current major limitation in our understanding of the tPA-plasmin system and BDNF in depression is the lack of larger clinical depression studies that investigate the association between PA, PAI-1, plasmin, proBDNF and mBDNF." (PMID 29348904, 2017). "Notably, PA-induced increases in BDNF have been recapitulated in unmedicated patients with MDD, elderly persons with remitted depression, and women with BP." (PMID 28529805, 2017). "Levels of BDNF in the prefrontal cortex of rats with depression-like phenotype were lower than those of rats without depression-like phenotype and sham-operated rats." (PMID 28600519, 2017). "BDNF decreases in expression and function in the PFC and hippocampus in animal models, which is crucial in the genesis of depression, as well as in the blood of patients with depression." (PMID 29181202, 2017). "The main finding of the present study is that, under baseline conditions, the relative protein levels of BDNF and its selective receptor trkB, measured by WB, are significantly lower in the dorsal hippocampus of depression‐vulnerable RLA rats versus depression‐resistant RHA rats." (PMID 29075579, 2017). "BDNF and its receptor tropomyosin receptor kinases B (TrkB) as well as its downstream target cAMP-responsive element binding protein (CREB) played crucial role in depression." (PMID 28694833, 2017). "We found that decreased GR expression and translocation, which mediated BDNF, TrkB and NR2B down-regulation in the spinal dorsal horn, contributed to the attenuating effect of OB-induced depression on mechanical allodynia and thermal hyperalgesia of neuropathic pain." (PMID 28579944, 2017). "Within this context, decrements in BDNF are not sufficient to effectuate depression in humans per se." (PMID 28928987, 2017).
depression (continued). "Although there are lines of evidence point out the relationship between BDNF and depression or cognitive function, but the association between the COX2 and cognitive impairment in depression is not very clear." (PMID 28415673, 2017). "According to our findings, BDNF binds to tropomyosin receptor kinase B (TrkB), the high affinity receptor for BDNF, and BDNF-TrkB activates (phosphorylates) ERK1/2 via the Ras-Raf-MEK-ERK cascade, which mediates survival, growth, differentiation, plasticity, and anti-depression." (PMID 29023414, 2017). "Anxiety-like behavior (light-dark test), depressive-like behavior (forced swim test), plasmatic levels of the brain-derived neurotrophic factor (BDNF, depression biomarker), and central glial fibrillary acidic protein (GFAP) expression (an astrocyte biomarker) were also evaluated." (PMID 28056040, 2017). "In the process, we confirmed that fluoxetine could improve the depression-like behaviors of PSD mice and upregulate the expression of BDNF in the hippocampus." (PMID 29097744, 2017). "Preclinical models showed that increasing influence of BDNF in VTA and ventral striatum may induce depression." (PMID 29217995, 2017). "Indeed, BDNF and IL6 appear to have opposing roles in depression - BDNF is thought to interact negatively with inflammatory processes in the brain and there is attenuation of BDNF availability with increased inflammation." (PMID 29070016, 2017). "Peripheral BDNF levels were decreased in patients with MDD patients but were not specific to MDD or the state of depression." (PMID 29387021, 2017). "Taken together, it is likely that the increased BDNF-TrkB signaling in the NAc, but not other brain regions, plays a key role in the depression-like behavior of α7 nAChR KO mice." (PMID 27821848, 2016). "Since Nrf2 KO mice showed decreased BDNF-TrkB signaling in the CA3, DG and PFC, we examined whether the TrkB agonist 7,8-DHF43, 44, 45, 46, 47, 48 shows antidepressant effects in depression-like phenotype of Nrf2 KO mice." (PMID 27470577, 2016). "Fluoxetine, a selective serotonin reuptake inhibitor (SSRI) also known as Prozac, is widely used against depression, potentially by activating cAMP response element-binding protein (CREB) and increasing brain-derived neurotrophic factor (BDNF) through protein kinase A (PKA)." (PMID 27598965, 2016). "As a similar interaction effect between the presence of a psychiatric diagnosis and BDNF was found on rostral ACC thickness, our findings may be driven by or related to depression and/or anxiety disorders." (PMID 27405617, 2016). "The present longitudinal study, which considered a history of MDE or excluded all cases with the history, suggests that BDNF is not a trait marker for MDD or other types of depression." (PMID 27070410, 2016). "One previous study indicated that serum levels of mature BDNF, but not proBDNF, were significantly lower in patients with depression than those of healthy control subjects." (PMID 27007747, 2016). "Chronic but not acute duloxetine treatment can also increase BDNF levels in the blood of patients with depression." (PMID 27757074, 2016). "Neurotrophic factors, particularly the brain-derived neurotrophic factor (BDNF), have important roles in the pathophysiology of depression and in the therapeutic effects of antidepressant treatment (Duman and Monteggia, 2006; Castrén and Rantamäki, 2010; Hashimoto, 2015)." (PMID 27757074, 2016). "DNA methylation levels of the BDNF promoter I and promoter IV were studied in patients with borderline personality disorder (BDP), whose disease phenotype is closely related to the depression and suicide phenotype." (PMID 27267954, 2016). "Cross-sectional studies have demonstrated that the brain-derived neurotrophic factor (BDNF) Val66Met single-nucleotide polymorphism moderates the association between exposure to negative life events and depression outcomes." (PMID 27621711, 2016).